DNMT3B (DNA methyltransferase 3 beta)
Diseases named in the same sentence as DNMT3B in open-access papers (continued):
Sharing a sentence is not in itself a finding about the gene and the disease.
bladder cancer (26 papers, 2009 to 2025). "In this study, we aimed to evaluate the effect of the polymorphisms rs2228611 of the DNMT1 gene and rs1569686 of the DNMT3B gene on the susceptibility to develop Bladder Cancer in the Algerian population." (PMID 38504781, 2024). "In the present study, we investigated the clinical significance of DNMT3B expression and the underlying mechanisms of DNMT3B in promoting the migration and invasion of bladder cancer." (PMID 33221743, 2020). "In the present study, we aim to evaluate possible implication of SNPs of the DNA methylation genes DNMT1 and DNMT3B in the occurrence of bladder cancer in the Algerian population." (PMID 38504781, 2024). "The role of DNMT3B in this process was also observed in bladder cancer upon DNMT3B knockdown inhibited migration and invasion." (PMID 36460706, 2022). "In bladder cancer, MAEL plays a critical oncogenic role in supporting cell EMT and invasion and bladder cancer metastasis via downregulation of MTSS1 through DNMT3B." (PMID 35513870, 2022). "H19 regulates the expression level of DNMT3B protein and epithelial-mesenchymal transition in bladder cancer." (PMID 34422802, 2021). "miR-502-5p inhibited the expression of CCND1, NOP14, and DNMT3B, the targets of miR-502-5p, by reducing cell migration in bladder cancer." (PMID 34288816, 2021). "It was also reported that H19 promotes epithelial-mesenchymal transition and metastasis of bladder cancer via H19/miR-29b/DNMT3B signaling pathway in cytoplasm." (PMID 34422802, 2021). "This study enhances our understanding of the mechanisms of DNMT3B and miR-34a in the migration and invasion of bladder cancer." (PMID 33221743, 2020). "Our present results suggest that DNMT3B silencing suppresses migration and invasion by upregulating miR-34a in bladder cancer." (PMID 33221743, 2020). "According to the level of DNMT3B protein expression, bladder cancer tissues were divided into the low-DNMT3B-expression group and the high-DNMT3B-expression group." (PMID 33221743, 2020). "Bisulfite genomic sequencing (BSP) analysis showed that the methylation ratio of the miR-34a promoter was lower in the low-DNMT3B-expression bladder cancer tissues compared to that in the high-DNMT3B-expression tissues." (PMID 33221743, 2020). "We found that DNMT3B expression was low in 10 bladder cancer tissues and high in 20 bladder cancer tissues." (PMID 33221743, 2020). "We examined 30 bladder cancer tissues and the level of DNMT3B expression was high in 20 tissues and low in 10 tissues." (PMID 33221743, 2020). "miR-34a expression was higher in bladder cancer tissues with low DNMT3B expression compared to those with high DNMT3B expression." (PMID 33221743, 2020). "Based on the total scores, DNMT3B was found to be weakly expressed in 10 bladder cancer tissues and highly expressed in 20 bladder cancer tissues." (PMID 33221743, 2020). "Since the role of DNMT3B in bladder cancer cell lines EJ and UMUC3 was undefined, we studied the effect of DNMT3B knockdown on the migration, invasion, and EMT in EJ and UMUC3 cells." (PMID 33221743, 2020). "In this study, we explored the correlation between miR-34a promoter methylation and DNMT3B expression in bladder cancer." (PMID 33221743, 2020). "DNMT3B expression in 30 bladder cancer tissues was assessed using tissue microarrays and scored independently by two senior pathologists." (PMID 33221743, 2020). "miR-34a expression was higher in bladder cancer tissues with low expression of DNMT3B than that in bladder cancer tissues with high expression of DNMT3B." (PMID 33221743, 2020). "In conclusion, DNMT3B silencing suppresses migration and invasion by epigenetically promoting miR-34a in bladder cancer." (PMID 33221743, 2020). "Consistent with this, ANG-MMP2 overexpression and DNMT3b underexpression correlated with reduction in disease free survival of human bladder cancer patients." (PMID 27317771, 2016).
bladder cancer (continued). "Our results indicate that the ANG gene is amplified in human bladder cancer, leading to reduced expression of DNMT3b and increased expression of MMP2." (PMID 27317771, 2016). "DNMT1 was over-expressed, whereas DNMT3B was downregulated in bladder cancer cells." (PMID 36077697, 2022). "Moreover, miR-451a promoter methylation regulated by DNMT3B expedited the progression of bladder cancer via the PI3K/AKT axis." (PMID 34783292, 2021). "Considering its function in de novo methylation, we aimed to investigate whether DNMT3B plays its role via microRNA (miR)-34a promoter methylation in bladder cancer." (PMID 33221743, 2020). "Together, our data indicate that the suppression of DNMT3B inhibits EMT in bladder cancer cells." (PMID 33221743, 2020). "Based on the results from bladder cancer tissues, we hypothesized that DNMT3B reduced the expression of miR-34a via miR-34a promoter methylation, which was verified using bladder cancer cell lines." (PMID 33221743, 2020). "In conclusion, our results have showed that the level of DNMT3B is positively correlated with the methylation ratio of the miR-34a promoter while DNMT3B silencing suppresses migration and invasion by epigenetically promoting miR-34a in bladder cancer cell lines." (PMID 33221743, 2020). "We also investigated whether DNMT3B promoted the migration and invasion of bladder cancer by epigenetically suppressing miR-34a." (PMID 33221743, 2020). "Since EMT promotes cancer cell migration and invasion, the suppression of miR-34a-Notch1 axis-induced EMT may be the regulatory mechanism of DNMT3B knockdown in suppressing the migration and invasion in bladder cancer." (PMID 33221743, 2020). "Our findings reinforce the importance of DNMT3B in bladder cancer and demonstrate that DNMT3B could be a therapeutic target for bladder cancer." (PMID 33221743, 2020). "Due to its function in de novo methylation, we hypothesized that DNMT3B might be a key factor that stimulates promoter methylation of the genes involved in bladder cancer progression and metastasis." (PMID 33221743, 2020). "To verify this hypothesis, we first analyzed the correlation between DNMT3B and miR-34a in bladder cancer tissues." (PMID 33221743, 2020). "The bladder cancer patients were divided into two groups by the protein levels of DNMT3B." (PMID 33221743, 2020). "Additionally, we found that the miR-34a inhibitor attenuated the inhibitory effects of DNMT3B knockdown on EMT, indicating that DNMT3B silencing suppresses EMT by upregulating miR-34a in bladder cancer." (PMID 33221743, 2020). "In order to investigate whether DNMT3B was involved in the migration and invasion of bladder cancer, we evaluated the effects of DNMT3B knockdown on the migration, invasion, and EMT in EJ and UMUC3 cells." (PMID 33221743, 2020). "We also verified whether DNMT3B was involved in the migration and invasion of bladder cancer via miR-34a." (PMID 33221743, 2020). "Interestingly, DNMT3B and miR‐502‐5p established a positive feedback loop in the regulation of bladder cancer." (PMID 31971654, 2020). "In addition, miR-451a is negatively regulated by DNMT3B in bladder cancer." (PMID 37284450, 2023). "However, limited reports are available describing DNMT3a and DNMT3b expression in bladder cancer." (PMID 27317771, 2016). "Although DNMT3b was classically considered an oncogene, due to its role in the hypermethylation of tumor suppressor genes during tumor progression in lung, breast, colon, and bladder cancers, several reports also indicate a tumor suppressor behavior at an advanced tumor stage." (PMID 26556862, 2016). "Other cancer-related genes at 20q include E2F1, which is specifically targeted by hrHPV-mediated degradation of pRb, PIGU, which may play a role in cell cycle control and was identified as an oncogene in bladder cancer, and DNMT3B, a de novo DNA methyl transferase." (PMID 19486517, 2009).
bladder cancer (continued). "The mRNA level of DNMT3B was higher and the level of miR-34a was lower in the EJ and UMUC3 bladder cancer cell lines compared to those in the T24 and BIU-87 bladder cancer cell lines." (PMID 33221743, 2020). "We first analyzed ANG, DNMT3b and MMP2 mRNA levels in human bladder cancer tissues by quantitative RT-PCR." (PMID 27317771, 2016). "To further define the role of ANG, DNMT3b and MMP2 in tumorigenesis, we collected 78 fresh bladder cancer samples from bladder cancer patients and extracted DNA and RNA for analysis." (PMID 27317771, 2016). "Studies investigating the association between polymorphism rs2228611 of the DNMT1 gene and rs1569686 of the DNMT3B gene and bladder cancer are rare almost none." (PMID 38504781, 2024). "We next investigated whether inhibiting miR-34a rescued the inhibitory effects of DNMT3B knockdown on the migration, invasion, and EMT in bladder cancer cells." (PMID 33221743, 2020). "This evidence demonstrated, for the first time, that H19 may function as a competing endogenous RNA (ceRNA) for miR-29b-3p and relieve the suppression of DNMT3B, leading to EMT and metastasis of bladder cancer." (PMID 33680956, 2020). "Interestingly, expression of ANG, DNMT3b and MMP2 is correlated with disease free survival in human bladder cancer." (PMID 27317771, 2016).
pancreatic cancer (26 papers, 2011 to 2025). "Similarly, the DNMT3B -149T allele resulted in increased gene expression levels in human pancreatic cancer cells." (PMID 31370354, 2019). "We showed that MG stress exerted its regulatory effect on DNMT3B levels in breast, colon and pancreatic cancer cells." (PMID 36998085, 2023). "Their analysis revealed a noticeable reduction in the expression levels of miR-29b, along with an upregulated mRNA expression of DNMT3b, within the pancreatic cancer tissues when compared to the corresponding paracancerous tissues." (PMID 37705098, 2023). "In pancreatic cancer, miR-29b targets and inhibits DNMT3B to suppress pancreatic cancer cell apoptosis." (PMID 37781524, 2023). "On the same line, miR29b is a miRNA that targets DNMT3A, and DNMT3B is downregulated in cancer of lymphoma and cancer of the pancreas." (PMID 36012258, 2022). "In pancreatic cancer, it was shown that the expression of mir29b was downregulated; meanwhile, DNMT3b was enhanced." (PMID 36012258, 2022). "Increased CXCR4 expression was achieved with the knock-down of DNA methyltransferase 1 (DNMT1) or DNA methyltransferase 3 beta (DNMT3B), or with the inhibition of DNA methylation by 5-aza-2-deoxycytidine (5-aza) in pancreatic cancer cells." (PMID 32110952, 2020). "DNA methyl transferases (DNMTs) play a very important role in DNA methylation in cells and we observed that DNMT1, DNMT3A and DNMT3B are themselves differentially methylated in pancreatic cancer." (PMID 28423671, 2017). "Increased expression of DNMT1, DNMT3A and DNMT3B was reported in pancreatic cancer, suggesting their role in pancreatic cancer development." (PMID 27999365, 2016). "Iodine-125 seed irradiation at a dose of 4 Gy decreases the protein expression of DNMT1 and DNMT3b in SW-1990 human pancreatic cancer cells." (PMID 24223648, 2013). "In this study we aimed to evaluate the expression of PPARγ, DNMT1, and DNMT3B and their correlation with clinical-pathological features in patients with pancreatic cancer (PC), and to define the effect of PPARγ activation on DNMTs expression in PC cell lines." (PMID 22919364, 2012). "They indicated that miR-29b could serve as a tumor suppressor in pancreatic cancer, highlighting its potential application as a therapeutic agent by targeting DNMT3B." (PMID 37705098, 2023). "In addition, a significant inverse correlation was observed between DNMT3B and miR-29b in pancreatic cancer tissues." (PMID 37705098, 2023). "In addition, NSUN6, NSUN7, and DNMT3B exhibited downregulated trends in pancreatic cancer." (PMID 35864471, 2022). "Our data put in evidence important differences in the periodicity and in the phase relationships of PPARG, DNMT1, and DNMT3B expression levels among the diverse cell lines examined, maybe related to a different genetic background in the diverse pancreatic cancer cells." (PMID 22966223, 2012). "Complementary knockdown experiments using 2 specific Nupr1 siRNAs to transfect pancreatic cancer cells (MiaPaCa2) decreased Dnmt1 mRNA levels (3.8 fold ± 0.7; p < 0.01), without affecting either Dnmt3a or Dnmt3b expression." (PMID 26617245, 2015).
ovarian carcinoma (25 papers, 2009 to 2026). A malignant neoplasm originating from the surface ovarian epithelium. "This study aimed to determine aberrant expression of DNMT1, DNMT3a, and DNMT3b in benign and malignant ovarian tumor tissues for their association with clinicopathological significance and prognostic value." (PMID 22768205, 2012). "However, only the loss of DNMT1 or DNMT3B significantly restored the ALDH1A2 expression in ovarian cancer cell lines." (PMID 31615043, 2019). "In addition, the data revealed that DNMT3b expression was significantly associated with lymph node metastasis of ovarian cancer (Pearson Chi-Square test, P = 0.027)." (PMID 22768205, 2012). "Furthermore, we aimed to study whether these DNMT1, DNMT3A and DNMT3B SNPs can be a genetic risk factor of ovarian cancer." (PMID 23666104, 2013). "More recently, the expressions of DNMT1, DNMT3A and DNMT3B were examined by immunohistochemistry in ovarian cancers and benign tumors." (PMID 37894317, 2023). "miR-20a-5p gain-of-function also inhibits autophagy in ovary cancer via DNMT3B (DNA methyltransferase 3 beta)-mediated DNA methylation of RBP1 (retinol-binding protein 1)." (PMID 36230953, 2022). "In recent studies, it was demonstrated that zebularine and 5-aza-dC down-regulate DNMT-1, DNMT-3a, and DNMT-3b in ovarian cancer cell lines." (PMID 34903991, 2021). "Consistent with the data of these reports, we observed that the mRNA levels of DNMT1, DNMT3A, and DNMT3B were elevated in ovarian cancer tissues compared to those in normal epithelial ovarian cells." (PMID 31615043, 2019). "The mRNA levels of DNMT1, DNMT3A, and DNMT3B were strongly elevated in ovarian cancer tissues compared to those in normal ovarian tissues, according to Oncomine." (PMID 31615043, 2019). "The overall high rate of expression for class I HDACs, DNMT1 and DNMT3b suggested that these mRNAs should be explored as predictive factors in ovarian cancer." (PMID 23420051, 2013). "In summary, our studies demonstrate that the mRNA expression of DNMT1, DNMT3b and class I HDACs was increased in ovarian cancers." (PMID 23420051, 2013). "The expression of DNMT1 and DNMT3b was assessed in situ on paraffin sections of normal ovarian tissues (n=8) and malignant ovarian tumors (n=22)." (PMID 23420051, 2013). "The data showed that expression of DNMT1, DNMT3a, and DNMT3b was observed in 76 (53.5%), 92 (64.8%) and 79 (55.6%) of 142 cases of ovarian cancer tissues, respectively." (PMID 22768205, 2012). "Furthermore, the ALDH1A2 gene was found to be hypermethylated via DNMT1 or DNMT3B in ovarian cancer cell lines, indicating that ALDH1A2 expression is regulated by epigenetic regulation via DNMT." (PMID 31615043, 2019). "Furthermore, silencing DNA methyltransferase 1 (DNMT1) or 3B (DNMT3B) restored ALDH1A2 expression in ovarian cancer cell lines." (PMID 31615043, 2019). "Our studies did not demonstrate an association of the DNMT3B rs1569686, rs2424913 and rs2424932 SNPs with ovarian cancer." (PMID 23666104, 2013). "Additionally, the results of immunohistochemical staining demonstrated that DNMT1 and DNMT3b were significantly increased in ovarian cancer samples." (PMID 23420051, 2013). "Similarly, the relative expressions of DNMT1 and DNMT3b mRNA in ovarian cancers (n=22) were significantly higher than those in normal tissues (n=8), particularly for DNMT1 (P<0.01)." (PMID 23420051, 2013). "Using PCR–RFLP and HRM analyses, we studied the prevalence of the DNMT1 rs8101626, rs2228611 and rs759920, DNMT3A rs2289195, 7590760, rs13401241, rs749131 and rs1550117, and DNMT3B rs1569686, rs2424913 and rs2424932 SNPs in patients with ovarian cancer (n = 159) and controls (n = 180)." (PMID 23666104, 2013). "The miR-29 family and predicted target genes were among the most strongly anti-correlated miRNA:mRNA pairs; over-expression of miR-29a in vitro repressed several anti-correlated genes (including DNMT3A and DNMT3B) and substantially decreased ovarian cancer cell viability." (PMID 22479643, 2012).